WWOX (WW domain containing oxidoreductase)
Diseases named in the same sentence as WWOX in open-access papers (continued):
Sharing a sentence is not in itself a finding about the gene and the disease.
T-cell acute lymphoblastic leukemia (1 paper, 2017). Acute lymphoblastic leukemia of T-cell origin. "Calcium ionophore and phorbol ester induce WWOX to undergo Ser14 phosphorylation, which leads to terminal maturation of T cell acute lymphoblastic leukemia via IκBα/ERK/WWOX signaling." (PMID 27845895, 2017).
tongue tumour (1 paper, 2017). "Salivary miRNA-134 expression levels showed concordance to the tumour expression levels; the upregulation of miRNA-134 in tongue tumour tissues has shown to be associated with an increase in nodal metastasis as well as mortality in HNSCC patients mediated via the downregulation of WWOX gene." (PMID 29245955, 2017).
tumor (217 papers, 2004 to 2026). "Despite WWOX's established role as a tumor suppressor, conclusive evidence linking germline WWOX loss‐of‐function variants to oncogenesis remains scarce." (PMID 41124647, 2026). "The missense P252A variant in the WWOX gene was selected for further analysis based on its homozygosity and previously reported tumor‐suppressive function." (PMID 41124647, 2026). "This study provides the first functional evidence demonstrating tumor suppressor inactivation of WWOX variants through in vitro and in vivo models, while mechanistically elucidating the molecular basis of WWOX functional impairment." (PMID 41124647, 2026). "We provide the first functional evidence that both variants completely abrogate WWOX's tumor‐suppressive activity." (PMID 41124647, 2026). "Somatic mutations in the WWOX gene have been found in various neoplasms, highlighting its role as a tumour suppressor gene." (PMID 39507621, 2024). "The WWOX gene encodes for a tumor suppressor, mainly correlating its function to cancer, but it is also associated with the CNS’s development and function, as well as with immune cell proliferation and maturation." (PMID 38542346, 2024). "Recent studies demonstrated that WWOX plays a pivotal role in the cellular response to hypoxia, a hallmark of the tumor microenvironment." (PMID 37445845, 2023). "This downregulation of WWOX expression is linked to increased cell survival, proliferation, migration, and invasion, promoting tumor progression and metastasis." (PMID 37445845, 2023). "Recently, increasing scientific interest has focused on dissecting the biological processes underlying this severe phenotype as WWOX encodes for a transcriptional regulator potentially involved either in tumor suppression or cell growth and differentiation." (PMID 35573960, 2022). "As our data shows and was reported by others, WWOX gene silencing is associated with cancer aggressiveness, epithelial-to-mesenchymal transition, tumor metastasis, and chemoresistance." (PMID 35290621, 2022). "Staining for WWOX protein expression in the tumors revealed that those developed in Wwoxf/+ KWC mice displayed reduced or lost WWOX expression at the tumor sites compared to the normal sites, suggesting a loss of Wwox heterozygosity at these sites." (PMID 36572673, 2022). "Our results underscore the role of WWOX as a driver tumor suppressor in PDAC and suggest that its loss or somatic deletion promotes tumorigenesis." (PMID 36572673, 2022). "The accelerated tumor growth observed in neuT tumors from complement-deficient mice was associated with reduced activation of the tumor suppressor WWOX and stronger Her2 oncoprotein expression." (PMID 35203439, 2022). "The tumor suppressor WWOX has been implicated in glucose homeostasis through regulating HIF1α and its target genes." (PMID 33520443, 2021). "SCAR12 is produced by mutations in the WWOX (WW domain containing oxidoreductase) gene, which has functions in DNA repair and acts as tumor suppressor gene." (PMID 33917666, 2021). "The extensive study of the molecular functions of WWOX has provided many other arguments, leaving little doubt that WWOX plays an important role in cancer, which would therefore be associated with tumor progression." (PMID 33946771, 2021). "The discovery of the WWOX gene was made first in humans and for many years its loss-of-function in humans was studied only in the context of its tumor suppression and adaptor protein functions." (PMID 34831305, 2021). "Loss of WWOX contributes to tumor progression and chemotherapeutic resistance through its interaction with several binding partners, including AP-2γ, STAT3, and ErbB4 among others." (PMID 33129329, 2020).
tumor (continued). "Dysregulation of WWOX has been implicated as playing a key role in tumor cell survival, DNA damage repair, and genomic stability." (PMID 33129329, 2020). "Tumor suppressor gene WWOX encodes WW-domain containing oxidoreductase, which is frequently found to be down-regulated in several cancers." (PMID 30781778, 2019). "Homozygous null mutation of tumor suppressor WWOX/Wwox gene leads to severe neural diseases, metabolic disorders and early death in the newborns of humans, mice and rats." (PMID 30158849, 2018). "WWOX was originally discovered by our laboratory and described by us and others as a putative tumor suppressor protein mostly associated with tumor progression, and therapy resistance in multiple cancer types." (PMID 30619736, 2018). "The downregulation of WWOX expression in advanced-stage tumor samples of HNSCC is associated with methylation of the WWOX promoter region but not with miR-134 expression." (PMID 28045433, 2017). "WW domain-containing oxidoreductase (WWOX), a tumor suppressor gene, is associated with the development of various cancers." (PMID 27655721, 2016). "WWOX is known to be a fragile site-associated tumor suppressor gene, and loss or down-regulation of WWOX expression has been shown to contribute to the development of cancer." (PMID 26862731, 2016). "This agreed with many tumor types affected by WWOX deletions, which suggests that the loss of WWOX at both genomic or expression level is an important role of cell development in carcinogenesis." (PMID 27501229, 2016). "WWOX was originally cloned as a putative tumor suppressor because of its frequent loss in cancer (reviewed in Gardenswartz and Aqeilan7)." (PMID 27551470, 2015). "As WWOX gene encodes four transcript variants and current studies support the role of WWOX variant 1 as a tumor suppressor, the controversies regarding the expression of WWOX in cancers are probably caused by variant 4, whose function remains to be elucidated." (PMID 23109895, 2012). "Epigenetic changes at fragile genes associated with highly expressed fragile sites, such as FHIT and WWOX, have been characterized in a number of tumours and suggested to be associated with expression of fragility." (PMID 16981993, 2006). "Therefore, this paucity of reported cancer‐associated loss‐of‐function variants positions WWOX as a non‐canonical tumor suppressor gene in current oncogenetic paradigms." (PMID 41124647, 2026). "However, a significant association is known to exist between progressive loss of WWOX expression and increased tumor grade/stage or accelerated cancer progression; this results in a greater chance of an invasive and aggressive status in BLCA." (PMID 33718178, 2021). "Moreover, allelic loss at WWOX-proximal locus 16q24 was found to be related to tumor progression in up to 45% of BLCAs." (PMID 34204827, 2021). "We found that the percent of neoplastic cells staining for WWOX was also significantly decreased in high-grade MCTs, supporting the idea that loss of WWOX may correlate with a more aggressive tumor phenotype." (PMID 33129329, 2020). "WWOX (MIM 605131) encodes a WW domain-containing oxidoreductase known to be involved in several cellular and biological processes, including tumor suppression, cell growth and differentiation, regulation of steroid metabolism, induction of apoptosis and central nervous system (CNS) development." (PMID 32581702, 2020). "WWOX can act as a tumour suppressor not only owing to its common loss in many human malignancies but also due to its tumour suppressive effect when overexpressed and the susceptibility to tumour formation in WWOX-mutant mice." (PMID 33113804, 2020). "There may be a tumor-associated family of transmembrane proteins, cancerous expression of which abrogates the tumor suppressor function of WWOX." (PMID 30214895, 2018). "We therefore, assessed whether targeting the proliferative/survival signals in WWOX-deficient cancer cells could help inhibit tumor progression." (PMID 29724996, 2018).
tumor (continued). "Moreover, WWOX deficiency in hepatocytes combined with diethylnitrosamine treatment increased the tumor burden, which was associated with increased HIF1α levels and target gene transactivation." (PMID 29724996, 2018). "WWOX protein might interact with several molecules that are associated with tumor progression and angiogenesis, including RUNX2, bcl-2, P73, c-Jun, and Dvl-2." (PMID 28977834, 2017). "Reestablishment of WWOX expression in WWOX-deficient, cancer-derived cell lines resulted in growth inhibition, apoptosis, and eventual inhibition of tumorigenicity, suggesting its tumor suppressor function." (PMID 27977694, 2016). "It remains unknown whether these neuronal defects result from impaired DDR function of WWOX or whether patients harboring WWOX null mutations are more sensitive to tumor development over their life span." (PMID 27977694, 2016). "WWOX loss could also be significant during tumor progression modulating gene expression thus leading to tumor promotion and metastasis." (PMID 26256646, 2015). "Similarly, we have identified a homozygous truncating germline mutation in WWOX, a gene so far considered a tumor suppressor gene, in a severe recessive neurodevelopmental syndrome." (PMID 24456803, 2014). "The deletion and mutation of WWOX may inhibit apoptosis and promote tumor occurrence and development." (PMID 23276146, 2012). "The WWOX gene encodes a WW-domain-containing oxidoreductase that acts as a transcriptional regulator and plays an essential role in various biological processes, including tumor suppression, cell proliferation, apoptosis induction, steroid metabolism, and central nervous system development." (PMID 39223676, 2024). "Finally, WWOX and AP-2γ overexpression (W/C) was associated with not only a decrease in tumor cell viability, proliferation potential, adhesion, clonogenicity and the ability to create spatial structures, but also an increase in apoptosis or intensified migration rate." (PMID 33718178, 2021). "ER stress response is also activated in hypoxic or nutrient-deprived tumours, and thus WWOX loss might be the key to multistep carcinogenesis that enables tumours reaching a macroscopic size to survive under conditions of cellular stress due to stimuli such as hypoxia." (PMID 28749468, 2017). "The results indicated that over‐expression of wild‐type WWOX significantly suppressed tumor growth in vivo, compared with the group of empty vector." (PMID 41124647, 2026). "IHC staining showed that the expression of WWOX protein was significantly lower in tumor tissues, compared with adjacent normal tissues." (PMID 41124647, 2026). "As a tumor suppressor, WWOX acts as a downstream effector of the tumor necrosis factor (TNF) signaling pathway." (PMID 40006511, 2025). "Although these findings provide strong mechanistic insights into the tumor-suppressive role of WWOX through modulation of RUNX2, direct investigations of this molecular pathway in ES have not been published." (PMID 41141138, 2025). "This ROS-mediated pathway leads to enhanced apoptosis and DNA damage in cancer cells, highlighting the potential mechanism through which WWOX exhibits tumor-suppressive activities." (PMID 40006511, 2025). "While initially identified as a tumor suppressor, WWOX plays a role in a wide range of pathways and processes, including neurodevelopment and possibly neurodegeneration." (PMID 41430078, 2025). "WWOX, a tumor suppressor that plays a role in apoptosis and inhibits WNT signaling, had the highest number of structural variants, with 7 variants in three cases." (PMID 40670673, 2025). "This analysis ultimately identified a gene containing the WW-domain containing oxidoreductase (WWOX) domain as a drug target for TSN’s anti-tumor effects, a finding that was further validated in subsequent experiments." (PMID 40223937, 2025).
tumor (continued). "VOPP1 facilitates the localization of WWOX protein within lysosomes, preventing its interaction with p73α, thereby suppressing apoptosis and promoting tumor progression." (PMID 40949794, 2025). "WW domain-containing oxidoreductase (WWOX) is a tumor suppressor gene located at a common fragile site." (PMID 40006511, 2025). "Upregulation of miR-134 activates WW domain-containing oxidoreductase (WWOX), a tumor suppressor that promotes apoptosis and suppresses tumorigenicity." (PMID 41465138, 2025). "Although normal mammary epithelium of these two mouse models expressed WWOX in most cells, conditional ablation of the indicated genes was enough for tumor development." (PMID 38499540, 2024). "WW-domain-containing oxidoreductase (WWOX) spans one of the most active common fragile sites FRA16D, and encodes a 46 kDa tumor suppressor that is altered in most human cancers." (PMID 38182577, 2024). "As a tumor suppressor gene and a scaffold protein, WWOX plays a crucial role in regulating multiple cellular processes, including cell growth, apoptosis, DNA repair, and maintenance of genomic stability." (PMID 38499540, 2024). "WWOX is a crucial tumor-suppressor gene involved in various cellular processes such as DNA repair, cell-cycle regulation, apoptosis, and transcriptional regulation." (PMID 37445845, 2023). "Previously known as a proapoptotic tumor suppressor, WWOX has been reported to be involved in epidermal homeostasis in normal human skin." (PMID 38203337, 2023). "WWOX is widely recognized as a tumor suppressor, and a substantial portion of WWOX functional investigations has elucidated its role in modulating cancer related pathways through interactions between proteins." (PMID 38203337, 2023). "WW Domain Containing Oxidoreductase (WWOX) protein acts as a tumor suppressor by interacting with TFAP2A and 2C." (PMID 37291585, 2023). "Tumor growth of DBTRG-05MG cells was aggravated following WWOX overexpression, but the opposite was found in T98G, U251MG, and U87MG." (PMID 36979157, 2023). "The decrease in WWOX expression, observed in diverse cancer types including lung and ovarian cancer, correlates with increased tumor metastasis and poorer prognosis." (PMID 38203337, 2023). "The WWOX protein is involved in several cellular processes, such as metabolism, DNA damage response, and tumor suppression 9-12." (PMID 37324196, 2023). "The localization of WWOX within these unstable chromosomal regions was the initial evidence pointing toward its role as a tumor suppressor gene." (PMID 38203337, 2023). "The hot genes with the most positive signal events in the normal-specific group were RBPJ, PFKFB3, CAMK1D, ACACB, and WWOX, whereas the hot genes in the tumor-specific group were SLC35F3, PCDH7, NF1, and RAB27B." (PMID 36895481, 2023). "In the list of downregulated DEGs, low CD27 expression in malignant plasma cells has been reported to be correlated with poor prognosis while the tumour suppressor gene WWOX has been found downregulated due to translocations or deletions." (PMID 37006302, 2023). "That is, reduced binding of endogenous WWOX with target proteins in organs and tumor lesions occurs, which allows enhanced cancer growth." (PMID 35883580, 2022). "The suppression of the transactivation function of RUNX2 by WWOX probably contributes to the tumor suppressor role of WWOX." (PMID 36271927, 2022). "CALML3 was found to be downregulated during tumor progression which would explain its increased level during WWOX overexpression but decreased level during AP-2γ overexpression." (PMID 35563688, 2022).